LY86-AS1 (LY86 antisense RNA 1)
Synonyms: FLJ33708; LY86-AS; LY86AS
Gene: Long non-coding RNA gene on chromosome 6 (6,346,076 to 6,622,791, reverse strand). Ensembl gene ENSG00000216863.
Diseases named in the same sentence as LY86-AS1 in open-access papers:
LY86-AS1 is named in the same sentence as 1 disease in open-access papers, as found by Europe PMC text mining. Sharing a sentence is not in itself a finding about the gene and the disease.
LY86-AS1 shares sentences with these, for which no sentence is quoted: cancer (1 paper).